Y_RNA (Y RNA )
Gene: Miscellaneous RNA gene on chromosome 7 (75,513,025 to 75,513,126, reverse strand). Ensembl gene ENSG00000200874.
Homologues: Orthologues: chimpanzee Y_RNA (98% identical), pig Y_RNA (72% identical). Paralogues in human: Y_RNA (99% identical), Y_RNA (92% identical), Y_RNA (89% identical), RNY3 (88% identical), RNY3P1 (87% identical), Y_RNA (86% identical), Y_RNA (85% identical), Y_RNA (84% identical), Y_RNA (83% identical), RNY3P13 (82% identical), RNY3P14 (82% identical), RNY3P16 (82% identical), and 94 more.